TNC (tenascin C)
Diseases named in the same sentence as TNC in open-access papers (continued):
Sharing a sentence is not in itself a finding about the gene and the disease.
breast cancer (continued). "For instance, the miRNA miR-335-5p, the top hub node in the network is already known to be a key regulator in suppressing breast cancer metastasis and migration through regulation of targets SOX4 and TNC." (PMID 26763900, 2015). "Primary breast fibroblasts isolated from normal breast tissue were transfected with individual TNC isoforms and co-cultured in the lower chamber of invasion assays with MCF-7 breast cancer cells." (PMID 19405959, 2009). "By further analysing above EMT-related RBPs and AS in breast cancer tissues in TCGA, it was found that the expression levels of ADAT2, C2orf15, SRP72, PAICS, RBMS3, APOBEC3G, NOA1, ACO1 and the AS of TNC and COL6A3 were significantly correlated with the prognosis of breast cancer patients." (PMID 38783078, 2024). "Conclusively, eight RBPs such as RBMS3 and AS of TNC and COL6A3 could be used as predictors of breast cancer prognosis." (PMID 38783078, 2024). "It was found in our study that RBM47, PCBP3, FRG1, SRP72 and other RBPs may regulate the AS of ITGA6, ADGRE5, TNC and other genes and affect the EMT process of breast cancer cells." (PMID 38783078, 2024). "RBM47, PCBP3, FRG1, SRP72 and other RBPs might regulate AS of ITGA6, ADGRE5, TNC and other genes and affect the EMT process of breast cancer cells." (PMID 38783078, 2024). "Moreover, the specific relation between TNC and CCL2 is also described, as both proteins are involved and highly overexpressed in the case of breast cancer." (PMID 37834140, 2023). "Although TNC is known to play a role in breast cancer metastases, we have not yet investigated the role of these nanobodies as function-blocking antibodies such as by studying their impact on tumor progression and/or metastatic dissemination." (PMID 37098922, 2023). "Our previous analysis of open databases showed that ITGA11 expression was correlated positively with PDGFRB, ACTA2, TNC, COL1A1, and COL1A3 in human breast cancer, and the immunostainings showed that α11, PDGFRβ, and TNC were colocalized to CAF subsets in human breast cancer stroma." (PMID 36003785, 2022). "In breast cancer, it was reported that ITGA11 promoted CAF invasive activity by interacting with PDGFRβ and promoting its downstream JNK activation, leading to the production of tenascin C, a pro-invasive matricellular protein." (PMID 34182990, 2021). "For the effect of the JNK pathway on ECM, a breast cancer study showed that the JNK pathway could increase the expressions of ECM proteins secreted phosphoprotein 1 (SPP1) and tenascin C (TNC)." (PMID 34063627, 2021). "Additionally, JNK signaling promoted stem cell properties, including sphere formation and invasion ability, and treatment of a breast cancer mouse model with paclitaxel-induced SPP1 and TNC expression via JNK signaling." (PMID 32283767, 2020). "For instance, tenascin-C, a protein of ECM involved in angiogenesis, invasion, and metastasis, has been recently identified as involved in the formation of the stem niche, relevant to favor lung colonization of breast cancer cells." (PMID 30532788, 2018). "Moreover, when we analyzed SPP1 and TNC expression in human breast cancer metastasis samples ranked according to JNK signature score, a marked increase in expression of SPP1 and TNC was observed in metastasis samples with high JNK activity (Fig EV4B)." (PMID 30190333, 2018). "PTPRN2, MERTK, TNC and SOX4 were identified to be targets of miR-335, AIB1 and CCND1 were the targets of miR-17-5p, and H-RAS and HMGA2 were verified as targets of let-7 in breast cancer." (PMID 30309377, 2018). "The aim of this study was to determine the changes in a panel of stromal proteins within the tumor, including THBS1, TNC, FN, SPARC and α-SMA, following neoadjuvant chemotherapy in newly diagnosed breast cancer patients using immunohistochemistry (IHC) staining." (PMID 27487140, 2016).
breast cancer (continued). "96-well plates were pre-coated with six ECM components that are commonly deregulated in breast cancer (collagen I, collagen IV, fibronectin, hyaluronan, laminin, tenascin C) with uncoated plastic as a negative control." (PMID 27556857, 2016). "Although having its main function in creating a metastatic niche and inducing WNT and NOTCH signaling pathways, tenascin C depletion did not correlate with a reduction of stem cell characteristics of the breast cancer cells in this study." (PMID 26539408, 2015). "Of particular interest, miR-335 was recently reported to suppress metastasis of human breast cancer via targeting of SO × 4 and tenascin C, however, without affecting its proliferation." (PMID 21592405, 2011). "In this study analysis of a series of breast cancer cell lines demonstrated expression of TNC-16 and/or TNC-14/16 in all oestrogen receptor (ER) negative lines characterised by more aggressive behaviour, but not in the ER-positive cell lines." (PMID 19405959, 2009). "By establishing the correlation network of differential RBPs and differential AS events, we found that RBM47, PCBP3, FRG1, SRP72, RBMS3 and other RBPs may regulate the AS of ITGA6, ADGRE5, TNC, COL6A3 and other cell adhesion genes, which may affect the EMT process of breast cancer cells." (PMID 38783078, 2024). "Similarly, in breast cancer, WT1-positive tumors were found to be more mesenchymal, and overexpression of WT1 in breast epithelial cells, HBL100, led to upregulation of mesenchymal markers, such as Vimentin (Vim) and Tenascin C (Tnc)." (PMID 36864480, 2023). "Drug-induced stress signaling as measured by pan JNK activation has been shown to induce TNC and osteopontin (OPN), counteracting its potential as anti-cancer treatment, but inhibition of JNK (thus downregulating TNC and OPN) could sensitize breast cancer patients to chemotherapy." (PMID 36102918, 2022). "For example, using an orthotopic mammary tumor model, in which grafted tumor cells were engineered to express high or low levels of tenascin-C, we observed not only more numerous TAM in tenascin-C high tumors, but that TAM were exclusively present inside “tracks” formed by tenascin-C deposition." (PMID 33718177, 2021). "Additionally, Tenascin-C promotes migration and anchorage independent growth of non-metastatic breast cancer cells, such as MDA-MB-435, and also regulates tumor angiogenesis by controlling the expression of vascular endothelial growth factor (VEGF)." (PMID 31362353, 2019). "Moreover, tenascin-W is present in the stroma of mouse mammary tumor models developing metastasis, whereas tenascin-C is absent from both non-metastatic tumors and normal mammary tissue." (PMID 29112161, 2017). "A breast cancer cell line, MCF-7, that does not express detectable levels of tenascin-C was used as a negative control to verify the role of sulfatide in the interaction between SCN and tenascin-expressing cancer cells." (PMID 25072631, 2014).
glioma (107 papers, 2008 to 2026). A benign or malignant brain and spinal cord tumor that arises from glial cells (astrocytes, oligodendrocytes, ependymal cells). "TNC is a member of the pathogenesis of glioma, interacting with several factors, most of which cause tumor progression." (PMID 39090080, 2024). "Both brevican and tenascin-C are glycoproteins in the human brain that are overexpressed in glioma cells and associated with a later tumor stage." (PMID 37174618, 2023). "Particularly, among the proteins over-expressed in GBM-sEVs, we noted the glioma-associated extracellular matrix antigen Tenascin C (TNC), the stemness-associated CD109 antigen, the tumor-associated CD44 antigen, the Ras suppressor protein 1 (RSU1)." (PMID 36009432, 2022). "TNC is overexpressed and correlated with tumor malignancy observed in many cancer types and is associated with glioma outcomes." (PMID 32708613, 2020). "Elevated TNC mRNA and protein in adult glioma is also associated with mesenchymal and classic glioma subtypes, as well as higher tumor histological grade, disease recurrence, local tumor invasion and poorer overall survival." (PMID 31092287, 2019). "Despite tenascin-C other ECM components were also associated with a more migratory phenotype of glioma, such as laminin, fibronectin, and collagen, but myelin biomembranes are also efficient substrates for migration." (PMID 31003495, 2019). "A query of recently published pediatric glioma genomic data demonstrates that TNC mRNA overexpression is associated with poorer overall and disease free survival, younger age, increased tumor grade, Histone H3 mutation and midline tumor location." (PMID 31092287, 2019). "In the present study, we show that the IL-33/ST2 signalling axis can directly cause TNC expression through the activation of its downstream signalling pathways, mainly NF-κB, to promote glioma progression." (PMID 31889095, 2019). "TNC encodes tenascin-C that contributes to the invasive nature of glioblastoma and the majority of high-grade gliomas, to the adhesion of medulloblastoma and to the malignant transformation of plexiform neurofibromas." (PMID 21726470, 2011). "Additionally, simultaneous silencing of TNC reduced or even reversed the glioma promotion caused by TDG overexpression." (PMID 39090080, 2024). "TNC is an extracellular matrix protein that is primarily associated with the regulation of cell adhesion, migration, and proliferation, and its sustained expression is associated with inflammation and a variety of tumors, including gliomas." (PMID 36292695, 2022). "Indeed, in mouse models and humans, it has been shown that increased ECM stiffness resulting from HA deposition and tenascin C (TNC) production is associated with higher glioma grade." (PMID 31632393, 2019). "A representative example is the GBI-10 aptamer, a single-stranded DNA sequence that binds tenascin-C (TN-C), a protein highly expressed on glioma cells." (PMID 41560835, 2026). "Confirmed via cytology, sEVs from the plasma of glioma patients exhibited enrichment of ephrin type-A receptor 2 (14.7-fold), tenascin C (22.7-fold), and glial fibrillary acidic protein (8.4-fold)." (PMID 41373835, 2025). "In humans, tenascin-C (TN-C) expression has been detected in more aggressive neoplasms of the central nervous system, such as gliomas and meningiomas." (PMID 39453053, 2024). "To validate the involvement of TNC in the malignant phenotype of TDG-induced gliomas, we established stable cell lines by transfecting siTNC into TDG-overexpressing cells for the rescue assay." (PMID 39090080, 2024). "In this scenario, recent studies demonstrated a role for the modulation of CD47 expression, a “don’t eat me” receptor expressed on glioma cells, in the recruitments of M2-like TAMs and in the upregulation of TNC expression via Notch pathway-mediated mechanism." (PMID 38969910, 2024).
glioma (continued). "Another essential component that favors invasion is tenascin C. Gliomas are characterized by higher expression of tenascin C, which binds toll-like receptor 4 (TLR4) and induces M2 polarization of macrophages and microglia." (PMID 38473812, 2024). "TNC, which is upregulated in mesenchymal glioblastoma subtypes with high NF-κB signaling activity, has been shown to promote glioma stem cell proliferation." (PMID 38390494, 2024). "Previous studies have identified several key components of the ECM, including hyaluronic acid (HA), fibronectin, thrombospondin, and tenascin-C, that are secreted by glioma cells and play a role in this process." (PMID 39033204, 2024). "Meanwhile, we further delved into the specific mechanisms of TDG-mediated active DNA demethylation leading to the overexpression of TNC and promoting glioma tumourigenesis by RNA-seq, ChIP-qPCR, and MeDIP-qPCR." (PMID 39090080, 2024). "A variety of monoclonal antibodies against TNC are now available and can also be combined with temozolomide, which can be targeted to fight gliomas." (PMID 39090080, 2024). "TNC is involved in and regulates glioma angiogenesis in two ways: on the one hand, TNC inhibits angiogenesis by blocking YAP signaling and endothelial cell behaviors through direct contact." (PMID 39090080, 2024). "The effect of major ECM proteins such as hyaluronic acid (HA), collagen, tenascin C (TNC), periostin, fibronectin, and laminin on immune landscape in glioma is presented." (PMID 38969910, 2024). "Our findings strongly implicate that TDG exerts a function similar to tumor-promoting factors, mediating the up-regulation of TNC expression, and is involved in glioma progression." (PMID 39090080, 2024). "TNC is a component of the glioma ECM that binds to integrin receptors, EGF receptor (EGFR), and SYNDECAN 4 (SDC4) and regulates angiogenesis, proliferation, and cell migration." (PMID 36707509, 2023). "Several ECM molecules involved in migration and invasion are proteoglycans (versican, brevican, cadherins) and glycoproteins (CD44, tenascin C, fibrinogen), which were found upregulated in higher grade gliomas." (PMID 37174618, 2023). "Tenascin-C can activate the Notch pathway to promote glioma proliferation by increasing ADAMTS15 and Jagged1 (JAG1) expression." (PMID 37325048, 2023). "In this review, we focused on the matricellular protein TNC and highlighted its significant implications in gliomas." (PMID 36033448, 2022). "The target gene tenascin-C (TNC) was obtained by screening the Chinese Glioma Genome Atlas (CGGA) and the Cancer Genome Atlas (TCGA) databases." (PMID 35371015, 2022). "SMOC1 was first discovered in 2002, is widely distributed in the basement membrane ECM of many tissues, and is known to be upregulated in oligodendrocytoma and astrocytic tumors and can inhibit the migration of glioma U87 cells induced by tenascin C." (PMID 36686480, 2022). "Accordingly, Vitronectin, Fibronectin, and Tenascin C expression is correlated with increasing invasiveness and a higher glioma grade." (PMID 35053605, 2022). "When complexed with 4Na or Ca, EDTA exhibited non-toxic anti-proliferative effects in the presence of soybean trypsin inhibitor (c6 glioma cells) and Tenascin C (u87 glioma cells)." (PMID 36540522, 2022). "Integrins interact with ECM components, such as collagen, brevican, tenascin-C, fibronectin, and thrombospondin, which leads to the adhesion and migration of glioma cells." (PMID 35327982, 2022). "High expression of tenascin-C correlates with cancer grade and poor prognosis in various cancers, including esophageal squamous cell carcinoma, glioma, gastric, prostate, breast and colorectal cancer." (PMID 35008401, 2022). "The stiff matrix promotes HIF1A expression in glioma cells and, as a result, increases tenascin C expression, which is critical for glioma aggression." (PMID 35205794, 2022).
glioma (continued). "Here, in light of its potential significance, we review the matricellular protein TNC in the glioma ECM, and highlight the implications of TNC in glioma progression, tumorigenesis, and treatment." (PMID 36033448, 2022). "Glioma cells express components such as tenascin-C, fibronectin, and thrombospondin, which support the adhesion and migration of glioma cells." (PMID 35832194, 2022). "Most tumors express high levels of this ECM glycoprotein and gliomas in particular have an enrichment of Tenascin-C (TN-C), which participates in tumor progression and correlates with tumor malignancy." (PMID 36276147, 2022). "For example, glioma cells produce let7, tenascin-C (TNC), and versican resulting in increased production of cytokines and matrix metalloproteases (MMP9 and MMP14) by GAMs." (PMID 34084145, 2021). "Based on a number of former studies, TNC participates in the pathogenesis of glioma via interaction with multiple factors, mostly resulting in tumor progression." (PMID 33876384, 2021). "TNC has been established as a protein mediator of microenvironment and glioma cell interaction ultimately facilitating and converging on integrin-mediated signaling." (PMID 35127517, 2021). "TNC acts as an oncogenic factor by promoting cancer cell proliferation and stemness while inhibiting apoptosis and chemosensitivity to paclitaxel in glioma via modulation of PI3K/AKT signaling." (PMID 33876384, 2021). "GSCs also have cross talk with microglia and recruit GAM at glioma tumor site; GSCs-triggered GAMs release pro-inflammatory cytokine IL-6 via TLR4 signaling which is activated by GSCs-produced tenascin-C to promote glioma growth." (PMID 34715891, 2021). "In summary, TNC acts as an oncogenic factor by promoting cancer cell proliferation and stemness while inhibiting apoptosis and chemosensitivity to paclitaxel in glioma by modulating PI3K/AKT signaling." (PMID 33876384, 2021). "A similar role for TNC has been identified in glioma, where co-culture of glioma cells alongside T-lymphocytes inhibited T-cell activation, again through α5β1 integrin signaling." (PMID 33187209, 2020). "TNC is also highly expressed in high-grade gliomas which correlates as well with the invasiveness of glioma cells." (PMID 32817625, 2020). "TNC was discovered in the early 1980s and initially referred to by different terms such as myotendinous antigen, glioma mesenchymal ECM, hexabrachion, TN, J1-200/220, cytotactin, and neuronectin." (PMID 33552066, 2020). "The vasculature within gliomas shows upregulated protein expression of the macromolecules periostin and tenascin C (TNC), which can prevent T cells from moving into glioma-associated vessels and prevent their migration into the brain parenchyma." (PMID 33193310, 2020). "In conclusion, we have validated that IL-33 can result in the expression of TNC through autocrine or paracrine modes of action in glioma cells via activation of some downstream signalling pathways and can then promote tumour progression." (PMID 31889095, 2019). "Upon TNC knockdown, glioma growth was significantly inhibited in mice bearing subcutaneous xenograft of U251 cells (***p < 0.001)." (PMID 31754182, 2019). "Our results indicate that TNC plays an important role in VM formation in glioma, suggesting that TNC is a potential therapeutic target for anti-angiogenesis therapy for glioma." (PMID 31754182, 2019). "In conclusion, we characterized TNC expression in pediatric glioma tissue and cell lines, including DIPG, with higher endogenous expression levels in tumors harboring the H3K27 M mutation." (PMID 31092287, 2019). "In this study, our key finding was that IL-33 increased TNC expression and promoted glioma invasion through the IL-33/ST2/TNC signalling axis with activation of NF-κB signalling." (PMID 31889095, 2019). "Our finding that TNC promotes VM formation by glioma cells further indicates an important role of TNC in glioma pathogenesis." (PMID 31754182, 2019).